INS (insulin)
Diseases named in the same sentence as INS in open-access papers (continued):
Sharing a sentence is not in itself a finding about the gene and the disease.
Insulin resistance (continued). "One metabolic consequence of obesity is insulin resistance, which results in increased insulin secretion from the pancreas." (PMID 38727260, 2024). "Together, we here demonstrate that GCA haploinsufficiency induces insulin resistance and defects of insulin signaling potentially through a GPX/PTEN axis in skeletal muscle." (PMID 39383215, 2024). "Insulin resistance occurs when target tissues, such as the liver, become less sensitive to the effects of insulin." (PMID 38212723, 2024). "In vitro, betaine reversed insulin resistance in primary human hepatocytes by increasing insulin-stimulated tyrosine phosphorylation of IRS1 and of Akt." (PMID 39119463, 2024). "These cytokines interfere with insulin signaling pathways, leading to exacerbated insulin resistance." (PMID 39519193, 2024). "In this study, decreased serum insulin concentrations and increased insulin resistance index (HOMA-IR) values were obtained in the diabetic rats." (PMID 38324798, 2024). "After three months, women with MBC experienced significant improvements in fasting blood glucose, insulin, insulin resistance, body weight, and body composition, effects that have been observed in healthy individuals." (PMID 38166036, 2024). "For example, pro-inflammatory cytokines are known to interfere with the insulin signalling route ultimately leading to insulin resistance and type 2 diabetes." (PMID 36795085, 2024). "Type 2 diabetes, on the other hand, occurs because of an increase in insulin resistance, which means that insulin becomes less effective." (PMID 39840001, 2024). "As such, in the presence of high insulin resistance, when insulin levels increase, the need for ATP also rises." (PMID 39768947, 2024). "Medications like metformin, an insulin sensitizer, have been shown to promote ovulation by lowering insulin resistance, reducing circulating androgen levels, and improving menstrual regularity." (PMID 39459443, 2024). "In this study, we observed an increase in Bacteroides in dogs with HAC, where insulin resistance is commonly seen due to elevated cortisol levels contributing to decreased insulin sensitivity." (PMID 39409832, 2024). "For instance, adipocytes laden with fat exhibit poor responsiveness to insulin stimulation leading to hyperinsulinemia (insulin resistance) and hyperglycemia." (PMID 38416754, 2024). "This is generally achieved by the activation of transitory and resident macrophages, and the secretion of immune mediators or humoral factors that contribute to decreased insulin signaling and increased insulin resistance." (PMID 38672413, 2024). "The patient, after NRP SPK, experienced short-term delayed pancreatic graft function requiring low-dose insulin treatment for 5 days post-transplant, most likely due to increased peripheral insulin resistance in obesity." (PMID 38930054, 2024). "A diet low in carbohydrates reduces insulin production and, consequently, hyperinsulinemia and insulin resistance, which are observed in most infertile women and men." (PMID 38392349, 2024). "AMPK activation has been shown to enhance glucose uptake independent insulin as well as reduce insulin resistance in skeletal muscle." (PMID 38611884, 2024). "T2DM is primarily attributed to insulin resistance coexists with insulin relative deficit owing to β-cells dysfunction." (PMID 38632264, 2024). "Ser/Thr phosphorylation of IRS-1 induces insulin resistance by interfering with the tyrosine phosphorylation cascade of insulin signaling." (PMID 39796441, 2024). "Hyperglycemia in lean individuals is generally due to insufficient insulin secretion as well as insulin resistance." (PMID 39512839, 2024). "As a compensatory mechanism, the pancreas increases insulin secretion into the bloodstream, leading to hyperinsulinemia and/or insulin resistance (IR)." (PMID 39595646, 2024). "Many women diagnosed with PCOS encounter insulin resistance, a condition where the body’s cells respond poorly to insulin." (PMID 39459564, 2024).
Insulin resistance (continued). "Specifically, clinical trials have demonstrated that forms of RS2 promote metabolic benefits, including increases in glucagon-like peptide-1 (GLP-1), decreases in circulating insulin and insulin resistance, attenuating fasting glucose levels, and weight loss." (PMID 39452917, 2024). "It has been found to increase serum insulin levels, improve glucose tolerance and insulin sensitivity, and has found to show promising results by reducing glucose levels and improving insulin resistance in a mouse model of NASH." (PMID 38347465, 2024). "It is well established that chronic elevated ROS contributes to insulin resistance, whereas low levels or acute generation of ROS from physiological stimuli, such as hormones, enhances insulin sensitivity." (PMID 39260699, 2024). "Excess weight is often comorbid with elevated insulin and insulin resistance, blood glucose, cholesterol, sex hormones, and IGF-1." (PMID 38446316, 2024). "Insulin resistance is a state of pathophysiological impairment characterized by reduced sensitivity and response of the body to insulin, which ultimately leads to hyperglycemia." (PMID 38755682, 2024). "Prediabetes with insulin resistance (decreased insulin function) results in decreased lipolysis process and reduced lipoprotein lipase activity." (PMID 39081429, 2024). "Metformin, a type of insulin sensitizer, is commonly used as a first-line anti-insulin resistance medication." (PMID 38665877, 2024). "As a result, the insulin signaling pathway is disrupted, leading to impaired glucose uptake by cells and exacerbating insulin resistance." (PMID 39519193, 2024). "In the case of dyslipidemia, the accumulated fat in the tissue extracellular mesenchyme reduces cellular sensitivity to insulin and triggers insulin resistance, leading to elevated blood glucose and HbA1c and the onset of type 2 DM." (PMID 38786962, 2024). "Vitamin D supplementation reduced blood glucose, insulin levels, and improved insulin resistance (IR) in rats in a prediabetic model, and this efficacy was proportional to the dose of vitamin D supplementation." (PMID 38650715, 2024). "Baseline leucine, valine, and tyrosine were predictors of 2 year increases in insulin, whereas tyrosine was a significant predictor of deteriorating insulin resistance over time." (PMID 39125441, 2024). "Patients with High blood glucose, due to insufficient insulin secretion or insulin resistance, cannot fully absorb and utilize glucose, but resorts to decomposing fat and protein for energy, resulting in excessive protein consumption and weight loss." (PMID 39267098, 2024). "SNPs in genes related to insulin signaling are potential candidates to explain PCOS's clinical manifestations since insulin resistance is a common finding in the disorder." (PMID 38468402, 2024). "If insulin resistance was present, pancreatic β-cells must secrete more insulin, resulting in compensatory hyperinsulinemia." (PMID 38974578, 2024). "Insulin resistance is a condition where the body’s cells become less responsive to insulin, impacting the uptake, metabolism, or storage of glucose, and has been associated with AS." (PMID 39649224, 2024). "induced insulin resistance in HepG2 cells by incubating them with 5000 nM insulin for 24h; subsequent glycogen content measurement revealed a significant decrease of glycogen synthesis in insulin resistance group." (PMID 39749015, 2024). "GLP-1 is one of the critical mechanisms for improving insulin resistance, primarily by reducing weight and enhancing peripheral tissue sensitivity to insulin." (PMID 38529045, 2024). "T2DM is a complex metabolic disorder marked by chronic hyperglycemia resulting from insulin resistance and impaired insulin secretion." (PMID 39877357, 2024). "In a state of insulin resistance, the liver is unable to suppress hepatic glucose production in response to insulin, thus leading to the severity of DNL." (PMID 39057041, 2024).
Insulin resistance (continued). "WD feeding significantly increased body weight and fat mass, increased fasting plasma insulin and homeostatic model assessment for insulin resistance score, and reduced glucose tolerance compared to control, chow-fed animals." (PMID 38729350, 2024). "In obesity and T2DM, abnormal insulin signaling is an important factor mediating the increase in insulin resistance." (PMID 38612572, 2024). "This can be interpreted as an improvement in insulin resistance status, with a decrease in insulin resistance-promoting hormones and an increase in insulin sensitivity markers as the infant matures and the nutritional status improves." (PMID 38341196, 2024). "Alternate-day fasting produces superior outcomes, specifically a decrease in fasting insulin levels and insulin resistance, compared to continuous CR in individuals with insulin resistance." (PMID 39203828, 2024). "There were both impaired first-phase insulin secretion and insulin resistance in the rats with pre-DM induced by an HFD." (PMID 38763955, 2024). "Insulin therefore plays an important role in glucose homeostasis, and impairment in insulin action, termed insulin resistance, leads to glucose intolerance and the development of metabolic dysfunction." (PMID 39590817, 2024). "Previous research has established that a defect in insulin sensitivity (that is, excess insulin resistance) contributes to GDM3,4." (PMID 38627562, 2024). "Brain insulin resistance (BIR) is secondary to decreased levels of insulin transport in the blood–brain barrier (BBB) and altered or impaired brain insulin signaling." (PMID 39518747, 2024). "The mechanisms behind these elevations involve chronic hyperglycemia due to insulin resistance, where cells become less responsive to insulin, and β-cell dysfunction, which impairs insulin production." (PMID 39479098, 2024). "Insulin hypersecretion is a driving factor for insulin resistance, obesity, and other aspects of metabolic dysfunction." (PMID 38131197, 2024). "Insulin resistance is a common underlying feature of T2DM and obesity which manifests from decreased insulin-stimulated glucose secretion and metabolism, and impaired suppression of hepatic glucose production as well as contribution from the gut microbiota." (PMID 39767626, 2024). "In this study, the O-C rats increased plasma insulin and insulin resistance, while obese rats with CME, FCME, and metformin showed a reduction of plasma insulin and insulin resistance similar to the normal control." (PMID 39598313, 2024). "Primary (FPG) and secondary outcomes [hemoglobin A1c (HbA1c), insulin, Homeostatic Model Assessment for Insulin Resistance (HOMA-IR), lipids/lipoproteins, vascular health, and Healthy Eating Index-2015] were measured before and after each condition." (PMID 38278217, 2024). "Inflammation in cells, distressed insulin signaling in the endothelium, hepatocytes, muscle, and adipose tissues promote endothelial dysfunction and insulin resistance." (PMID 38672494, 2024). "The effect of these interventions on fasting blood sugar and insulin levels, insulin resistance (IR), and insulin sensitivity were determined." (PMID 39618714, 2024). "Meanwhile, deletion of IGF-1R leads to elevation of insulin levels, insulin resistance and high glucose levels in the young male mice." (PMID 39273348, 2024). "The effectiveness of metformin in improving insulin sensitivity, a critical aspect of managing insulin resistance, further underscores the need for integrated treatment strategies that combine medication with targeted dietary interventions." (PMID 38786729, 2024). "It achieves blood glucose control effects by improving insulin sensitivity while reducing insulin resistance." (PMID 38884020, 2024). "Insulin resistance is associated with the development of hypertension, whereas there were rare studies comparing various non-insulin based insulin resistance (NI-IR) indices for the possibility of hypertension among young and middle-aged adults." (PMID 38566188, 2024).
Insulin resistance (continued). "Tirzepatide is a medication that improves insulin sensitivity, which can be evaluated indirectly through fasting biomarkers such as glucose and insulin and the homeostasis model assessment of insulin resistance (HOMA2-IR)." (PMID 38987789, 2024). "Cases had significantly higher metabolic markers like fasting insulin, Homeostasis Model Assessment of Insulin Resistance (HOMA-IR) index, and lipid profiles, whereas systolic blood pressure although showing recognized differences did not significantly differ." (PMID 39429362, 2024). "Type 2 diabetes is a complex metabolic disorder characterized by chronic hyperglycemia resulting from insulin resistance and impaired insulin secretion." (PMID 38421977, 2024). "In the case of diabesity additional insulin administration impacts not only insulin resistance but also body weight by direct and indirect effects." (PMID 38579770, 2024). "There is no doubt that protein synthesis significantly contributes to the physiological modulation of insulin signaling and insulin resistance." (PMID 39749015, 2024). "Insulin resistance impairs human trophoblast invasion in vitro, while insulin sensitizers promote appropriate trophoblast migration and invasion." (PMID 38397936, 2024). "Previous 1-year exposures to PM10 and NO2 were associated with elevated fasting blood glucose, Hemoglobin A1c, insulin, and insulin resistance." (PMID 39425159, 2024). "In another investigation, the prolonged consumption of a HFD led to elevated serum insulin levels, induced insulin resistance and facilitated enhanced fat deposition within the liver." (PMID 38892352, 2024). "Concurrently, the heightened pro-inflammatory environment contributes to the establishment of liver insulin resistance, disrupting the normal insulin signaling cascades within hepatocytes." (PMID 38689728, 2024). "This inflammation results in reverse fat storage and severe inflammatory damage in organs like the liver, while also impairing insulin signaling and reducing tissue sensitivity, ultimately leading to insulin resistance." (PMID 39179999, 2024). "Although the reduction of IDE in the setting of insulin resistance is typically linked to hyperinsulinemia, our findings showed that the decrease in IDE content was coincide with a lower plasma insulin level." (PMID 38975085, 2024). "In obesity and type 2 diabetes, prolonged high circulating insulin levels induce insulin resistance in adipocytes, disrupting lipid homeostasis and increasing lipolysis and FAO72,73." (PMID 39386724, 2024). "Brain insulin resistance, like systemic IR, is characterized by a diminished response of brain cells to insulin and reduced receptor uptake across the blood-brain barrier." (PMID 39261457, 2024). "Vitamin D has been implicated in the pathogenesis of insulin resistance and type 2 diabetes mellitus (T2DM), due to its effects on insulin secretion and sensitivity, inflammation, and calcium homeostasis." (PMID 39276209, 2024). "The decrease in postpartum insulin release and the increase in insulin resistance are significantly correlated with the elevation of NEFA." (PMID 39881718, 2024). "Among lipid species associated with changes in LVMI, changes in most of them were also associated with changes in other cardiometabolic factors (e.g., insulin, insulin resistance)." (PMID 39405119, 2024). "In fact, there are several studies that report an improvement of cognitive function after administering intranasal insulin in healthy patients and in patients with T2DM and an association between olfactory dysfunction and insulin resistance." (PMID 39735414, 2024). "Insulin resistance is known as an impaired insulin action in target organs, which eventually leads to a relative insulin deficiency." (PMID 38649684, 2024). "The insulin tolerance test (ITT) showed that Adgra3 overexpression alleviated the insulin resistance of HFD mice." (PMID 39718208, 2024).
Insulin resistance (continued). "Further correlation analyses of values at baseline demonstrated correlations between IAPP levels and various metabolic and inflammatory plasma markers, in particular insulin, insulin resistance, CRP, and GGT." (PMID 39062913, 2024). "Betulinic acid was also effective at ameliorating TNF-α-induced insulin resistance by preventing the negative regulator of insulin signaling and inflammation-activated protein kinase in adipocytes, thus potentially relieving insulin resistance." (PMID 39063310, 2024). "Insulin resistance (IR) denotes the incapacity of normal plasma insulin concentrations to adequately elicit glucose uptake by peripheral tissues, encompassing skeletal muscles and adipose tissue." (PMID 38792408, 2024). "The administration of apelin improves insulin sensitivity in obesity and diseases related to insulin resistance." (PMID 39457235, 2024). "In the male group, cut-off points for the VAT/SAT ratio were determined for the presence of hypertriglyceridemia (1.64), for the presence of insulin resistance (1.876), and for a fasting insulin concentration ≥ 10 mU/mL (1.939)." (PMID 38732548, 2024). "Type 2 diabetes mellitus (T2DM) is a chronic metabolic disorder characterized by inadequate insulin secretion and insulin resistance, leading to dysregulation of glucose homeostasis in the bloodstream." (PMID 39130628, 2024). "Norepinephrine release due to reduced arterial filling in HF impairs insulin sensitivity and glucose tolerance, aggravating insulin resistance." (PMID 39337658, 2024). "T2DM, a metabolic disorder, is characterized by hyperglycemia, insulin resistance, and impaired insulin secretion." (PMID 38595695, 2024). "The central role of insulin resistance and decreased insulin secretion in the pathophysiology of T2DM is well established." (PMID 39519454, 2024). "DM in lipodystrophic patients is characterized by severe insulin resistance and high levels of circulating insulin, leading to elevated triglyceride levels." (PMID 38633761, 2024). "The inhibition of this pathway can lead to abrogated insulin function, impaired insulin secretion, and the development of insulin resistance, resulting in hyperglycemia." (PMID 39070139, 2024). "The pathogenesis primarily involves the relative insufficiency of insulin secretion by pancreatic β-cells and the insensitivity of tissues and organs to insulin, which triggers insulin resistance (IR)." (PMID 38982402, 2024). "Subjects with T2DM showed lower insulin responses and lower subsequent II values than healthy subjects or subjects with insulin resistance." (PMID 38474713, 2024). "Hyperglycemia will eventually result when beta-cell secretion of insulin is unable to make up for insulin resistance." (PMID 38397782, 2024). "Western blot analysis was employed to investigate the effects of LPS administration and insulin treatment on insulin resistance (IR) in the hippocampus." (PMID 39073013, 2024). "For instance, M. charantia stimulates insulin resistance and improves glucose absorption, whereas G. sylvestre secretes more insulin and helps to rebuild pancreatic β-cells." (PMID 39493778, 2024). "Studies have demonstrated that blocking TLR4 can improve the insulin-dependent intake of glucose, alleviating insulin resistance induced by obesity in mice." (PMID 38275739, 2024). "NEU1 engages in the regulation of insulin signaling in multiple ways, including facilitating the initiation of insulin signaling, reversing insulin resistance, and cross-talking with MMP9." (PMID 39194692, 2024). "Bariatric surgery has been shown to promote the restoration of physiological insulin secretion within weeks and to ameliorate insulin resistance during long-term follow-up." (PMID 38791525, 2024). "Lifestyle modifications, including regular physical activity, healthy dietary habits, weight management, and stress reduction, play a crucial role in improving insulin sensitivity and mitigating the adverse effects of insulin resistance on metabolic health." (PMID 38920999, 2024).